RN7SKP65 (RN7SK pseudogene 65)
Gene: Miscellaneous RNA gene on chromosome 12 (57,977,965 to 57,978,277, reverse strand). Ensembl gene ENSG00000222210.
Homologues: Orthologues: chimpanzee 7SK (94% identical). Paralogues in human: RN7SKP79 (74% identical), 7SK (73% identical), RN7SKP102 (73% identical), RN7SKP189 (73% identical), RN7SKP217 (72% identical), RN7SKP4 (71% identical), RN7SKP137 (71% identical), RN7SKP180 (70% identical), RN7SKP203 (70% identical), RN7SKP44 (70% identical), RN7SKP78 (70% identical), RN7SKP9 (70% identical), and 284 more.